ARB2BP (ARB2 family member B, pseudogene)
Synonyms: LOC131909; FLJ45679; formerly FAM172B; FAM172BP
Gene: Transcribed processed pseudogene on chromosome 3 (101,521,891 to 101,522,979, forward strand). Ensembl gene ENSG00000175841.
Subcellular location: Membrane